CLEC9A (C-type lectin domain containing 9A)
Description:
Functions as an endocytic receptor on a small subset of myeloid cells specialized for the uptake and processing of material from dead cells. Recognizes filamentous form of actin in association with particular actin-binding domains of cytoskeletal proteins, including spectrin, exposed when cell membranes are damaged, and mediate the cross-presentation of dead-cell associated antigens in a Syk-dependent manner.
Synonyms: CD370; DNGR1; UNQ9341; HEEE9341; DNGR-1
Tractability: Antibody: UniProt predicts a signal peptide or a membrane-spanning region.
Gene: Protein-coding gene on chromosome 12 (10,030,678 to 10,066,031, forward strand). Ensembl gene ENSG00000197992.
Subcellular location: Membrane
Gene Ontology:
Biological process: positive regulation of cytokine production; receptor-mediated endocytosis
Cellular component: cell surface; membrane
Genetic constraint (gnomAD): Loss-of-function variants: 20 observed, 28.77 expected, observed/expected ratio (o/e) 0.7, 90% interval 0.49 to 1.01. The upper end of that interval is the gene's LOEUF score, 1.01, which puts it in group 4 of 6, group 1 being the genes least tolerant of losing a copy. Missense variants: 223 observed, 262.4 expected, observed/expected ratio (o/e) 0.85, 90% interval 0.76 to 0.95. Synonymous variants: 102 observed, 91.42 expected, observed/expected ratio (o/e) 1.12, 90% interval 0.95 to 1.32.
Homologues: Orthologues: chimpanzee CLEC9A (99% identical), macaque CLEC9A (91% identical), dog CLEC1B (71% identical), rabbit CLEC1B (61% identical), rat Clec9a (60% identical), mouse Clec9a (59% identical), guinea pig CLEC9A (54% identical), zebrafish si:ch211-170d8.8 (19% identical), Drosophila melanogaster rgn (18% identical), zebrafish si:dkey-26c10.5 (17% identical), zebrafish si:ch211-193e13.5 (17% identical), Caenorhabditis elegans clec-146 (14% identical), and 1 more. Paralogues in human: OLR1 (28% identical), CLEC12B (27% identical), CLEC7A (24% identical), KLRF1 (23% identical), CLEC1B (22% identical), KLRK1 (22% identical), CLEC1A (21% identical), CLEC12A (21% identical), KLRB1 (20% identical), KLRG1 (20% identical), KLRC1 (20% identical), KLRC2 (19% identical), and 11 more.
Diseases named in the same sentence as CLEC9A in open-access papers:
CLEC9A is named in the same sentence as 48 diseases in open-access papers, as found by Europe PMC text mining. Sharing a sentence is not in itself a finding about the gene and the disease. The quoted sentences say what the papers report.
melanoma (10 papers, 2020 to 2026). A malignant, usually aggressive tumor composed of atypical, neoplastic melanocytes. "The human equivalent CD141+ CLEC-9A+ DCs have been found in TDLNs and were responsible for the cross presentation and activation of anti-tumour T cells in melanoma patients." (PMID 34141724, 2021). "Promisingly, the co‐delivery of αGalCer and tumor antigens to cDC1s using nanoparticle‐based vaccine covered with anti‐CLEC9A antibodies promotes antitumor responses both in vivo in mouse model and ex vivo from PBMC of melanoma patients." (PMID 33282290, 2020).
viral infections (9 papers, 2014 to 2023). "CLEC9A/DNGR-1 binds to F-actin exposed on dying cells and while it does not increase antigen transfer, it enhances T cell responses toward cell-associated material and in viral infections." (PMID 30416504, 2018). "We therefore reasoned that loss of Clec9a on migratory APCs might strengthen the connection between apoptosis of LECs and archived antigen exchange and presentation in the context of viral infection." (PMID 29229919, 2017). "The distinctive capacity of lung CD103+ DCs to respond to DAMPs (F-actin) via Clec9a and viral infection via TLR3 provides a plausible mechanism for priming the inflammatory immune responses to RV infection." (PMID 35173718, 2022). "CLEC9A is reported to induce antitumor responses and modulate cytotoxic T lymphocyte responses to virus infection in mice; however, the mechanisms underlying the influence of EBV infection on the CLEC9A+ DC-related immune response in NPC remain to be elucidated." (PMID 32686767, 2020). "Thus, together with signaling via Clec9a, the lung CD103+ DCs have a unique functional property to respond to dead, necrotic cells and viral infections simultaneously." (PMID 35173718, 2022). "Of note, the recently described CLEC9A+/BDCA3+ DC subset can also release high amounts of INF-α, suggesting that, upon viral infection, they may play a key role in promoting NK cell cytotoxicity in peripheral tissues, such as skin, liver, lung, and intestine." (PMID 24782864, 2014). "Moreover, it has been shown that CLEC9A+/BDCA3+ DCs have the dual capacity to produce both IL-12 and type I IFN, thereby enabling both NK cell activation and Th1 polarization, which could be significant for a protective immune response against viral infections." (PMID 24782864, 2014).
breast carcinoma (6 papers, 2020 to 2024). "F-actin has been reported to promote antigen presentation through the F-actin receptor Clec9A on dendritic cells in a breast cancer model." (PMID 37751306, 2023). "The correlation between low Clec9A expression and poor outcomes in lung adenocarcinoma and breast cancer highlights the important role played by cells expressing this receptor." (PMID 37626903, 2023). "Consequently, CD8+ T-cell effector (Teff) score, comprising gene expression of IFNG, PRF1, CD8A and CD8B, and BATF3-DC score, calculated with the expression level of BATF3, IRF8, THBD, CLEC9A, and XCR118 were markedly increased in the high SLAMF6 group than in the low SL AMF6 group in breast cancer." (PMID 38287061, 2024).
atherosclerosis (5 papers, 2020 to 2025). A disease characterized by the build-up of fatty material and calcium deposition in the arterial wall resulting in partial or complete occlusion of the arterial lumen. "Therefore, upon CLEC9A deletion, the increased expression of IL10/IL-10 in the BM and CD8α+ DCs seem to be the main cause of reduced recruitment or the activation of macrophages in plaque sites, as well as the alleviation of atherosclerosis." (PMID 39528464, 2024). "Notably, in Apoe−/− Clec9a −/− mice fed an HFD, a significant reduction in atherosclerosis was observed." (PMID 38397127, 2024).
lung adenocarcinoma (4 papers, 2017 to 2023). A carcinoma that arises from the lung and is characterized by the presence of malignant glandular epithelial cells. "However, the role of CLEC9A in lung adenocarcinoma (LUAD) remains unknown." (PMID 34616670, 2021).
influenza (3 papers, 2017 to 2023). An acute viral infection of the respiratory tract, occurring in isolated cases, in epidemics, or in pandemics; it is caused by serologically different strains of viruses (influenzaviruses) designated A, B, and C, has a 3-day incubation period, and usually lasts for 3 to 10 days. "Studies comparing Clec9a and DEC-205 targeting in mice via mAb-antigen conjugates showed that despite raising similar CD8+ T cell responses, Clec9a targeting induced better protection in an influenza challenge model." (PMID 37662903, 2023). "Furthermore, we show that targeting a “universal” influenza Ag to Clec9A, as a priming step in a heterologous prime-boost strategy, leads to strong protection from influenza infection." (PMID 29263886, 2017).
lymphoma (3 papers, 2019 to 2023). A malignant (clonal) proliferation of B- lymphocytes or T- lymphocytes which involves the lymph nodes, bone marrow and/or extranodal sites. "A strong antitumor activity was also observed when a nanobody against the cDC1 marker Clec9A was used as adapter in murine melanoma, breast carcinoma and lymphoma models and against human lymphoma in humanized mice without any detectable toxic side effects 164,169." (PMID 31695800, 2019).
nasopharyngeal carcinoma (3 papers, 2022 to 2025). A carcinoma arising from the nasopharyngeal epithelium. "In addition, some studies have shown that the abnormal CLEC9A gene expression after radiotherapy of nasopharyngeal carcinoma (NPC) is closely related to the prognosis of head and neck squamous cell carcinoma (HNSCC)." (PMID 36202899, 2022). "One example is the discovery of CLEC9A+ DCs in NPC; the CLEC9A+ DCs are reported to be negatively correlated with the DNA level of Epstein–Barr virus (EBV), which has been suggested to be a contributing factor to the development of nasopharyngeal carcinoma." (PMID 40954554, 2025).
systemic candidiasis (3 papers, 2014 to 2025). "Because Clec9aΔSyk mice were used as homozygotes in these experiments and therefore lacked DNGR-1 expression, we confirmed that DNGR-1 deficiency does not impact on susceptibility to candidiasis by assessing fungal burden in infected Clec9aegfp/egfp mice." (PMID 25033445, 2014).
Autoimmunity (2 papers, 2010 to 2024). The occurrence of an immune reaction against the organism's own cells or tissues. "A previous study reported that the deletion of the Trex1 gene in Clec9a-expressing cells is sufficient to cause autoimmunity." (PMID 39254994, 2024). "Furthermore, selective loss of the Trex1 gene in Clec9a-expressing cells was sufficient to induce autoimmunity, indicating that deletion of Trex1 in cDC1 is sufficient to drive autoimmunity." (PMID 39254994, 2024).
COVID-19 (2 papers, 2021 to 2022). A disease caused by infection with severe acute respiratory syndrome coronavirus 2. "Severe COVID-19 is also associated with depletion in the number of pDCs and CD141+ (CLEC9A+) DCs from the blood of patients." (PMID 36369012, 2022). "Severe COVID-19 patients were characterized by having an increased pro-apoptotic pathways in pDCs, lower level of TLR9 in pDCs, decrement in DHX36 expression in CLEC9a+ DCs, decreased expression of MHCII related gene in CD1c+ DCs and decrement of ISG in monocyte subsets." (PMID 36369012, 2022).
malaria (2 papers, 2018 to 2019). Malaria is a serious and sometimes fatal disease caused by a parasite that commonly infects a certain type of mosquito which feeds on humans. "At the first stage, anti-CLEC9A antibodies were used to target malaria antigens to CD8α+DCs to efficiently prime malaria-specific CD8+ T cells." (PMID 31379818, 2019).
ovarian carcinoma (2 papers, 2021 to 2023). A malignant neoplasm originating from the surface ovarian epithelium. "Nevertheless, to the best of our knowledge, this is the first study to demonstrate the effectiveness of murine CD8α+ DCs in an ovarian cancer mouse model, suggesting that cDC1 vaccines represented by CD141+ Clec9a+ cells may be an effective immunotherapy in patients with ovarian cancer." (PMID 36596856, 2023).
ovarian tumors (2 papers, 2019 to 2023). "In ovarian tumors, XCR1 was expressed in the majority (~80%) of BDCA3+ cDC1s, suggesting enrichment of XCR1+ cDC1s in tumors and possibly, an enrichment of a more mature cDC1 DC population since Clec9a and BDCA3 are reported to also be expressed in pre-DCs, while XCR1 was not." (PMID 37942313, 2023).
cerebral malaria (1 paper, 2021). A sequestration of Plasmodium falciparum in the brain, which can cause coma and/or seizures. "In infections by another apicomplexan, Plasmodium falciparum, an absence of CLEC9A+ dendritic cells led to a strong reduction in brain CD8+ T cells, which was accompanied by resistance to experimental cerebral malaria." (PMID 33789945, 2021).
cervical cancer (1 paper, 2025). A primary or metastatic malignant neoplasm involving the cervix. "For example, CXCL8, CLEC9A, and TAB2 have been identified as crucial mRNA biomarkers related to immune microenvironment alterations in cervical cancer." (PMID 40003691, 2025).
chordoma (1 paper, 2023). Chordomas are rare malignant tumors arising from embryonic remnants of the notochord in axial skeleton. "The presence of two distinct subclusters of DCs in chordoma lesions, namely, CLEC9A DCs and activated DCs, underscores their crucial role as major contributors to the immune response against cancerous growth." (PMID 37784253, 2023).
colorectal tumor (1 paper, 2022). "Expression of the four chemokines was positively correlated with the two DC markers [integrin alpha X (ITGAX) and CLEC9A] in human colorectal tumor samples." (PMID 36654820, 2022).
hyperreactivity (1 paper, 2022). "Our recent work shows that CD103+ DCs and Clec9a are required for hyperoxia-induced pro-inflammatory responses to RV infection and airway hyperreactivity." (PMID 35173718, 2022).
lung carcinoma (1 paper, 2021). "We initially investigated cancers related to CLEC9A and found that CLEC9A had the highest correlation with lung cancer." (PMID 34616670, 2021).
myeloma (1 paper, 2022). "Unsupervised hierarchical clustering of osteocytes using RNA-seq gene expression data showed a response-specific gene expression signature, including four candidates: Clec9a, Riken, Adgrg5, and Ciita that were upregulated in the osteocytes from myeloma-bearing mice." (PMID 35760800, 2022). "There were no obvious correlations between mRNA levels of Clec9a, Riken, or Adgrg5 in osteocytes and the bone intensity in myeloma-bearing mice." (PMID 35760800, 2022).
oral cancer (1 paper, 2021). "This preliminary study aims to gain insight into the clinical and pathological relationship of clec9a expression in oral cancer and to explore survival patterns for future studies." (PMID 34415004, 2021). "The present preliminary study is the first investigation to study the presence of Clec9a+ DCSs in the TME of oral cancer." (PMID 34415004, 2021). "This preliminary study aims to understand the clinical and pathological relationship of clec9a expression in oral cancer and to explore survival models for future studies." (PMID 34415004, 2021). "Key words:Clec9a, dendritic cells, tumor microenvironment, oral cancer, immunotherapy." (PMID 34415004, 2021). "However, no previous research has studied the role of clec9a+ dendritic cells (DC) in oral cancer, and this research is the first to do so." (PMID 34415004, 2021).
pancreatic cancer (1 paper, 2022). "Immune infiltration (CD8+ cells, CD3+ cells, CD11c+ cells, Clec9a+ cells) and STING expression were also detected by multiplex IHC staining in pancreatic cancer patients’ tumor tissues (NSMAD4 negative = 43, NSMAD4 positive = 38)." (PMID 35064757, 2022).
primary immunodeficiency (1 paper, 2021). "The similar genes of CLEC9A were linked to functional networks involving positive regulation of interleukin-12 production, plasma membrane and CD40 receptor binding, primary immunodeficiency, intestinal immune network for IgA production, and cell adhesion molecules pathways." (PMID 34616670, 2021).
skin cancer (1 paper, 2023). "Our results show that a marked correlation between the CD103+DC signature (IRF8, FMS‐like tyrosine kinase 3 ligand, CLEC9A, CLNK, XCR1, BATF3, and ZBTB46) and chemokines C‐X‐C motif chemokine ligand 9, CXCL10, and CD8A in a mouse model with DMBA/TPA‐induced skin cancer." (PMID 36891351, 2023).
systemic fungal infection (1 paper, 2025). "Other studies have shown that CLEC9A activates the negative regulatory signal SHP-1 to dampen neutrophil-mediated immunopathology during systemic fungal infection." (PMID 40980891, 2025).
tumor (96 papers, 2015 to 2026). "In this study, we found that high CD74 concentration in HPCs was associated with a decreased proportion of CLEC9A(+) DCs, which suggested a potential tumor-promoting role of CD74 in HPCs." (PMID 39118044, 2024). "In contrast to XCR1, surface expression of Clec9a was undetected in the human dissociated tumor samples, likely due to Clec9a sensitivity to clipping from enzymatic digestion based on loss of Clec9a expression in PBMCs treated with Collagenase." (PMID 37942313, 2023). "These autophagosomes comprise tumor-associated antigens and, on the surface, express C-type lectin domain family 9 member A (CLEC9A) ligands that facilitate endocytosis by antigen-presenting cells (APCs)." (PMID 32344837, 2020). "Indeed, we have previously shown that sGsn−/− mice control MCA205 LA‐OVA tumours better than WT mice because of increased DNGR‐1(CLEC9A)‐dependent cDC1‐cross presentation of dead cell‐associated tumour antigens." (PMID 40745918, 2025). "CLEC9A is associated with prognosis and tumor immune microenvironment of LUAD, suggesting that CLEC9A may be considered as a novel biomarker for LUAD." (PMID 34616670, 2021). "Bispecific forms of selicrelumab that specifically target DCs (via CD11c, DEC-205, or CLEC9A arms) have shown potent anti-tumor activity in preclinical models, suggesting that DC activation is not the cause of the observed dose-limiting toxicities." (PMID 41086813, 2025). "For example, CLEC9A, a C‐type lectin receptor selectively expressed on cDC1s, has been used as a delivery route for tumor antigens." (PMID 40667699, 2025). "NK cell-derived XCL1 has been strongly implicated in the direct recruitment and activation of Clec9a+XCR1+ cDC1s into solid tumors, with cDC1s being essential for tumor antigen cross-presentation in tumor-draining lymph nodes." (PMID 40410571, 2025). "CLEC9A quickly internalizes and directs antigens into the cross‐presentation pathway, although tumor‐secreted gelsolin can impair its function." (PMID 40667699, 2025). "Tumor vaccines utilize anti-CLEC9A antibodies to specifically deliver the immunogenic tumor antigen NY-ESO-1 to human CD141+ DC cells for anticancer therapy." (PMID 39703499, 2024). "In WT mice, DEC205 and Clec9A-targeted OVA immunization results in a significant reduction in tumor GFP." (PMID 38594284, 2024). "An exciting new perspective has arisen from work by the Reis e Sousa lab demonstrating that tumours exploit the systemic actin scavenging system to prevent cross-presentation of tumour antigens by DCs via DNGR1/Clec9a." (PMID 38223410, 2024). "Here, we describe a method to target a TAP specific siRNA to resident Clec9a expressing cross-presenting cDC1 cells in mice which led to inhibition of tumor growth, dispensing with the need to isolate and expand cDC1 in vitro." (PMID 38231450, 2024). "cDC1s express high levels of DNGR-1 (also known as CLEC9A), a receptor that binds to exposed F-actin in dying tumor cells and facilitates antigen cross-presentation." (PMID 38545114, 2024). "C-type lectin domain family 9 A (CLEC9A)-cDC1+ DCs can regulate tumor immune surveillance and establish an important link between metabolism and immunity, serving as a therapeutic target for skin cancer." (PMID 39118044, 2024). "Targeting antigens to cDC1 in the form of peptide epitopes or whole antigen covalently linked to Clec9a Ab elicited CD8 + cytotoxic T cell responses as well as humoral and CD4 + T cell responses in mice, reduced viremia, and inhibited tumor growth." (PMID 38231450, 2024). "Second, we demonstrate that entinostat treatment promotes DC maturation within the tumor and induces CLEC9A, CD103, and CD40L expression in peripheral myeloid cells, indicating increased DC maturation and antigen processing, migration, and cross-presentation." (PMID 39532835, 2024). "Previous research focused primarily on DEC-205 and Clec9A, demonstrating their ability to augment the immune response and inhibit tumor growth." (PMID 38339158, 2024).